IL6 (interleukin 6)
Diseases named in the same sentence as IL6 in open-access papers (continued):
Sharing a sentence is not in itself a finding about the gene and the disease.
tumor (continued). "Cytokines are closely associated with tumor progression and immune response, and there is evidence that IL-6 promotes distant metastasis in ovarian cancer." (PMID 36741380, 2022). "IL6 expressed in MDA-MB-231 cells is associated with a chronic inflammatory tumor microenvironment and resistance to therapy." (PMID 35337112, 2022). "In PDAC, increased circulating levels of IL6 have been linked to tumour progression through modulating the TME and are generally associated with poorer clinical outcome." (PMID 36138073, 2022). "These tumor-associated macrophages (TAMs) secrete anti-tumor cytokines IL-6, IL-8 and IL-10 and matrix metalloproteinases (MMPs) which regulates neo-vasculogenesis in TME." (PMID 36253762, 2022). "It has been found that tumor-derived exosome miRNA-1247-3p can induce the activation of tumor-associated fibroblasts and make them secrete cytokines such as IL-6 and IL-8 to promote lung metastasis of liver cancer." (PMID 34980158, 2022). "Tumor-associated macrophages and cancer-associated fibroblasts secrete IL-6 that favors via JAK/STAT3 the migration and invasion of CRC cells." (PMID 36139106, 2022). "Second, further analysis validated these results that both PEA and AM11095 inhibited both the secretion of IL-6 and IL-8 inflammatory cytokines, which are important in tumor–associated inflammation." (PMID 36564457, 2022). "It is well-established that tumor-associated macrophages (TAMs) enhance the cancer progression and metastasis via the release of a various cytokines including IL-6." (PMID 35954156, 2022). "The main inflammatory factors associated with tumours include interleukin 6 (IL-6), interleukin 10 (IL-10), interleukin 1β (IL-1β), tumour necrosis factor alpha (TNF-α) and C-reactive protein (CRP)." (PMID 36482346, 2022). "The findings here expand the concept of commensal paracrine growth support by IL-6 over and above that of stromal-derived IL-6 from M2 polarized tumor-associated macrophages and mesenchymal stem cells." (PMID 35565421, 2022). "Recent evidence has indicted that IL‐6 secreted by tumour‐associated macrophages enhances metastatic colonisation of CRC cells." (PMID 36068649, 2022). "CBD attenuates chronic inflammation by completely inhibiting the production of inflammatory cytokines by the tumor microenvironment, including IL-1β, IL-6, interferon-β (IFN-β), and TNF-α, all implicated in initiation and progression of several cancers." (PMID 35456540, 2022). "Serum IL-6 levels have been also studied and can be associated with tumor stage, size, metastasis, and survival in different cancer types." (PMID 35683629, 2022). "Addition of TGF-β and IL-6 caused a threefold higher IL-17 expression in CD8+ T cells from tumor-bearing mice than from naïve mice." (PMID 35954312, 2022). "In OSCC patients, serum IL-6 levels are associated with increased tumor burden and aggressiveness, meaning that serum IL-6 can be a post-treatment prognostic marker after the treatment." (PMID 35740551, 2022). "Remarkably, most of the 20 prioritized ligands such as APP, EGF, and IL6, were associated with the process of tumor formation, progression, and invasion as well as confronting the anti-tumor immune response." (PMID 35812726, 2022). "Increased levels of IL-6 and other chemokines have been associated with GC growth, and IL-6 serum level has been shown to increase in parallel to tumor progression and to be correlated with survival." (PMID 35328248, 2022). "The tumor-promoting effect of IL-6 largely depends upon STAT3 activation; IL-6-deficient mice have reduced tumor growth and have abrogated STAT3 activation, suggesting the importance of IL-6 and STAT3 signaling in promoting colorectal tumorigenesis." (PMID 35205671, 2022).
tumor (continued). "iCAF subsets also produce certain cytokines, especially IL-6, which presents a pro-tumor function and is closely associated with chemoresistance and poor prognosis." (PMID 35681617, 2022). "We have observed that IL-6, Stat3, PD-1 and PD-L1 are associated not only within the signaling pathways but also with multiple immune cells and tumor microenvironment." (PMID 36454780, 2022). "In colitis associated colorectal cancer and hepatocellular carcinoma, tumor promotion is supported by IL-6 in a STAT3-dependent signaling mechanism." (PMID 35327456, 2022). "IL-33 deficiency or blockade led to reduced tumour Il4, Il6 and Il13 expression, and correlated with reduced tumour mast cells." (PMID 36263033, 2022). "After being polarized, tumor-associated macrophages (TAMs) secrete IL-6, which binds to its receptor on CSCs and activates the STAT3 pathway, promoting CSC expansion and activation of the expression of stem-related genes, such as Sox-2, Oct-3/4 and Nanog." (PMID 36497411, 2022). "Pro-inflammatory cytokines are released by tumor-associated inflammatory cells, such as IL-1, IL-6, TNF, and VEGF, which further influences the tumor progression and metastasis." (PMID 35964079, 2022). "IL6 signaling in tumor-associated macrophage enhances tumor cell survival in hypoxia conditions more prevalent in DDLPS than WDLPS that promote tumor progression and resistance to therapy." (PMID 35313831, 2022). "In a multivariable Cox regression model that included established preoperative available variables (age, sex and clinical tumor stage), higher pretreatment plasma levels of both IL6 and IL6sR were independently associated with worse RFS, CSS and OS." (PMID 34023914, 2022). "TNF-α is the cytokine that most consistently associated with tumor cell killing through activation of the transcription factor NF-κB and subsequent production of IL-1β, IL-6, IL-8 and IL-17." (PMID 35493517, 2022). "Studies further showed that the forced expression of IL-17A in the lung promotes tumor proliferation through IL-6 and tumor-associated neutrophils and that IL-17A mediates resistance to therapeutic programmed cell death protein 1 (PD-1) blockade." (PMID 35883573, 2022). "Several other factors produced by tumor or tumor-associated cells, like prostaglandin E2, extracellular adenosine, IL-10 and IL-6, further directly or indirectly prevent NK cell activation." (PMID 36045670, 2022). "4-M2d macrophages that represent a new M2 subgroup, also known as tumor-associated macrophages (TAMs), are activated by IL-6 and adenosines." (PMID 35205204, 2022). "IL-6 promotes tumor survival by suppressing immune surveillance through the recruitment and stimulation of tumor-associated myeloid-derived suppressor cells and neutrophils." (PMID 35626018, 2022). "Another study indicated that 8-hydroxyguanine (8-OHG) released from ferroptotic cells recruits and activates tumor-associated macrophages (TAMs) to secrete IL-6 and nitric oxide synthase 2 (NOS2), promoting tumorigenesis of KRAS-driven PDAC." (PMID 35664778, 2022). "Intriguingly, there was a trend for fewer KRAS –mutant cancers in the group with decreasing IL-6 levels and better treatment outcomes, pointing towards a possible association between IL-6 changes and tumor mutations." (PMID 35681606, 2022). "We then mechanistically linked this stromal IL6/LIF expression with tumor ER signaling by demonstrating that IL6/LIF signaling both increases tumor cell ERα expression and induces ER reporter gene activation." (PMID 36230597, 2022). "We next examined the effects of PrLZ S40A mutation on cell proliferation and tumor growth under IL-6 and SCH772984 treatment." (PMID 35194188, 2022). "In vitro studies have linked interleukin-6 (IL-6) to poor prognosis in BC via activated Janus kinase (JAK)/STAT tumor signaling, leading to an aggressive phenotype." (PMID 36369506, 2022).
tumor (continued). "On the other hand, IL-6-deficient mice have shown decreased tumor growth and increased tumor-infiltrating immune cells in the TME." (PMID 36361914, 2022). "IL-6 is an important cytokine linked to proliferation, differentiation, and maturity of cells, making this molecule a promising target for many anti-tumor therapies." (PMID 35659296, 2022). "LMP1-mediated glycolysis enhances the production of IL-1β, IL-6, and GM-CSF, the proliferation of tumor-associated MDSCs, and the inhibition of T-cells and NK cells, which lead to tumor immunosuppression." (PMID 36303138, 2022). "IL-6 has been proposed as a predictor of malignancy in multiple types of cancer where it is associated with tumor progression and decreased overall patient survival." (PMID 35703345, 2022). "These tumor-associated stromal cells also secrete a number of pro-tumorigenic factors, such as stromal-derived factor-1α, IL-6, IL-8, vascular endothelial growth factor, matrix metalloproteinases, and tenascin-C." (PMID 36271354, 2022). "The proinflammatory cytokines interleukin-6, expressed by tumour-associated macrophages, have been reported to be important to the development and progression of HCC by activating the transcription factor STAT3 and NF-κB pathways." (PMID 35255845, 2022). "IL-6 is mainly secreted in the tumor cells and tumor associated fibroblast and many studies have reported its immunopathogenicity and its signaling in tumor growth, metastasis, and therapeutic resistance in BC." (PMID 36547062, 2022). "EV-associated IL-6 functions as a stroma-tumor messenger, activating the JAK/STAT3 and TGFβ signaling pathways in tumor cells and promoting pro-aggressive behaviors." (PMID 36266345, 2022). "Within the CCA microenvironment IL6 can be produced by Kupffer cells, tumor-associated macrophages, cancer-associated fibroblasts (CAFs) and also by tumor cells." (PMID 35619118, 2022). "Increased levels of IL-6 occur also during muscle wasting in CC, and IL-6 inhibition is able to prevent muscle mass loss induced by tumor growth." (PMID 35881303, 2022). "This pro-tumor activity was associated with fibroblast production of the paracrine signaling factor IL-6 and was dependent on the expression of the heparan sulfate proteoglycan CD44v3 on the vesicle surface." (PMID 36106109, 2022). "Cytokines that were associated with tumor growth and metastasis (IL-1 and IL-6) are upregulated, particularly in canine metastatic mammary carcinoma samples." (PMID 36291791, 2022). "IL‐6 secretion is accompanied by increased Fos‐related antigen 1 deacetylation transcriptional activity, leading to cancer stem cell‐like properties and tumor progression associated with poor prognosis." (PMID 35791509, 2022). "This was not very surprising since the key hallmark of iCAFs is secreting inflammatory factors such as IL-6, which have been well-studied for their tumor-promoting capability." (PMID 36627901, 2022). "IL-6 has been implicated in tumor development and resistance to therapy in diverse cancer types, including through its effects on the immune system." (PMID 34711820, 2021). "A common requirement for the secretion of IL-6 from tumour-associated macrophages (TAM) of the intestine and the liver is an autocrine EGFR activation loop." (PMID 34047814, 2021). "Some of these pro-inflammatory cytokines such as IL-6, IL-8 and IL-23 are implicated in tumor progression and metastasis." (PMID 33923976, 2021). "IL-6 was found to be secreted by tumor-associated fibroblasts, and conditioned media from fibroblasts activated STAT3 in NPC cells." (PMID 34885950, 2021). "Studies showed a prevalence of M1 cells subtype among the tumor-associated macrophages in epithelial serous ovarian cancer microenvironment and are also associated with increased IL-6 levels in patients with advanced stages." (PMID 34912809, 2021). "Inflammation is strongly associated with various types of cancer, and IL-6 is a major cytokine released in the tumor microenvironment." (PMID 34945780, 2021).
tumor (continued). "IL-6, a cytokine found in high concentrations in the tumour microenvironment, has been implicated in causing chemoresistance in cancers." (PMID 34063891, 2021). "Tumor-associated cells are a potent source of immunomodulating molecules, i.a., pro-inflammatory cytokine IL-1, IL-6, TNF that are involved in the stimulation of key tumor-promoting factors as STAT3 and NF-κB." (PMID 34203461, 2021). "MSCs treated with conditioned media from M1 macrophages were found to promote tumor growth in a mouse model by converting tumor-associated macrophages into immunosuppressive M2 type by IL-6 secretion." (PMID 34681692, 2021). "For instance, IL-2, IL-15, and IL-21 are reported to promote tumor suppression in melanoma, whereas IL-1, IL-4, and IL-6 are associated with tumor progression in breast, prostate, and lung cancer." (PMID 33800170, 2021). "IL-6 is upregulated in several cancers (breast, colorectal, ovarian, lung, and pancreas cancers) in both the tumor tissue and in the patient’s serum and is often associated with advanced disease and poor prognosis." (PMID 33670492, 2021). "Tumor-associated macrophages (TAMs), cancer-associated fibroblasts (CAFs) or myeloid-derived suppressor cells (MDSCs) are major sources of IL-6 and play an important role in invasiveness and metastasis." (PMID 34445170, 2021). "In nude mice, IL-17 was found to promote tumorigenicity of human cervical tumours, which was linked to increased levels of IL-6 and IL-8 and macrophage recruitment at the tumour site." (PMID 34336101, 2021). "During studies on p62 functions unlinked to autophagy, it has been shown that p62 loss in the stroma drives tumor progression through activation of IL-6 in cancer-associated fibroblasts." (PMID 33902430, 2021). "F. nucleatum, which has tumor-promoting and NF-κB-activating effects, is also associated with IL-6 in CRC." (PMID 33578830, 2021). "Chemokines and their receptors and JAK-STAT signaling, both of which were associated with CRP/IL6 in our study, are involved in the inflamed immune cell–enriched tumor microenvironment." (PMID 34572592, 2021). "In aggressive metastatic ovarian carcinoma, tumor-associated macrophages (TAMs) are involved in the secretion of IL-6 which induces EMT via activation of STAT3." (PMID 34220337, 2021). "The experimental data showed that oral nutritional supplementation decreased the tumor growth associated with lower serum IL-6 levels and attenuated MDSC recruitment." (PMID 34578883, 2021). "Tumor-associated macrophages (TAMs) promote tumor progression by secreting IL-6 to activate IL-6/STAT3 signals in adjacent HCC stem cells in liver tissue microenvironments." (PMID 34976809, 2021). "The Octamer-binding transcription factor 4 (OCT4) is modulated by inflammatory cytokine interleukin-6 (IL-6) and is highly associated with tumor recurrence and poor prognosis of HCC." (PMID 34948424, 2021). "Inflammatory markers such as CRP, TNF-α, and IL-6 are associated with higher tumor grade and risk of mortality in CRC patients and are elevated in the blood of CRC patients compared to healthy controls." (PMID 34239993, 2021). "IL-6 is secreted by various cancer cell types and cancer-associated fibroblasts, causing chronic inflammation in tumours, which then binds IL-6R to form the IL-6/IL-6R complex." (PMID 33855091, 2021). "Recent studies have demonstrated that the pro-inflammatory cytokine IL-6, produced in the tumor-bearing state, is associated with promotion of metastatic colonization of colon cancer cells with dysfunctional anti-tumor immunity." (PMID 34722510, 2021). "The IL-6 expression associated with tumor progression, invasiveness and resistance to chemotherapy in CRC cells have been also extensively reported." (PMID 34096454, 2021). "It was also shown in the study that tumor size in the liver was smaller in monocyte-specific IL-6-deficient mice than in wild-type mice." (PMID 34576053, 2021).
tumor (continued). "EMT can be even induced by growth factors (such as TGFβ) and cytokines such as IL-6, which can be secreted by tumor cells but also activated by tumor-associated macrophages (TAMs)." (PMID 34768901, 2021). "We performed an unbiased mass spectrometry-based secretome analysis and identified several factors including IL-6 being secreted from tumor cells and cancer-associated fibroblasts (CAFs)." (PMID 34671021, 2021). "High levels of IL6, a well-known cytokine exerting also a pro-tumorigenic effect, have been found in the serum of people with PC and have been associated with tumor stage and survival." (PMID 34205944, 2021). "Studies have shown that bone marrow stem cells secrete IL-6, and tumor cells themselves and tumor-associated macrophages (TAMs) also release IL-6." (PMID 34976809, 2021). "Culig postulated in his review that serum IL-6 can act as an attractant for tumor cells and is linked to aggressive tumors." (PMID 34357036, 2021). "Studies with murine cancer models and genetic deficiencies in IL-6 or STAT3 have substantiated their role in several different tumor types." (PMID 33651821, 2021). "Interleukin-6 (IL-6) has been identified as a prominent factor secreted by tumor cells and cancer-associated fibroblasts isolated from cancer patients." (PMID 34671021, 2021). "Within the GC TME, IL-6 is produced by tumour-associated fibroblasts and tumour cells as well as immune cells." (PMID 34944729, 2021). "Knock out of IL-6 decreased the platelet counts and reduced tumor burden in a colitis-associated cancer model." (PMID 34722319, 2021). "Serum concentrations of IL-6 have been reported to be increased in diverse types of cancers and seem to be associated with tumor progression and prognosis." (PMID 33461943, 2021). "Higher numbers of mature DCs, CD4+ T cells, and CD8+ T cells were present in tumor sites of IL-6 deficient mice compared with wild-type mice, thus underlining the pivotal role of IL-6 in tumorigenesis." (PMID 34671021, 2021). "The results showed that particular addictive behavior (represented by smoking status), weak sleep scores, higher age, and more advanced tumor stage were significantly associated with increased serum IL-6 concentrations." (PMID 34681685, 2021). "IL-2Rα, TNF RI, M-CSF, and VEGF correlated with tumor size, IL-8 was associated with tumor grade, and IL-6 appeared to be correlated with tumor size, grade, and metastases." (PMID 34359785, 2021). "We did identify a strong positive association between SAA and IL6 expression in tumour biospecimens (Spearman r = 0.55, p < 0.0001)." (PMID 34203378, 2021). "The underlying mechanism of the relationship between CRP and cancers are that tumor growth can cause tissue inflammation, which make cancerous cells secrete interleukin 6 (IL-6) and stimulate CRP production in liver 35-37." (PMID 33613752, 2021). "Since HCC has a close association with IL-6 and its poor prognosis, many modalities have been carried out to mitigate the effects of IL-6-induced tumor progression." (PMID 35127527, 2021). "In the context of cancer, tumour-derived succinate induced migration and IL-6 production in tumour-associated macrophages, but also increased Arg1 expression, a marker of both “M2”-type and tumour-associated macrophages." (PMID 33995417, 2021). "For example, IL-4 and IL-6 secretion of CAFs accounts for the infiltration of tumor-associated macrophages (TAMs) and other immunosuppressive myeloid cells that promote immune-suppression." (PMID 33806802, 2021). "IL-6 is a well-known pro-inflammatory factor frequently up-regulated in serum and associated with tumor progression." (PMID 34638245, 2021). "In regards to IL-6, with unchecked inflammation being a hallmark of the tumor microenvironment, elevated levels of this cytokine can be found in tumor tissues of numerous cancers which have linked IL-6 to aggressive tumor growth and metastasis." (PMID 34504657, 2021).